AGT (angiotensinogen)
Diseases named in the same sentence as AGT in open-access papers (continued):
Sharing a sentence is not in itself a finding about the gene and the disease.
Hypertension (continued). "With respect to angiotensinogen, our data point towards an upregulation of the renin-angiotensin-aldosterone axis in women with MI even when controlling for the presence of hypertension and medications upon admission." (PMID 33831096, 2021). "Our previous study showed that trichostatin A, a HDAC inhibitor, prevented neonatal DEX-induced programmed hypertension accompanied with decreases of AGT, ACE, and ACE2." (PMID 33669059, 2021). "The results of the present study indicate that the TNF‐α activation of TNFR1 suppresses intrarenal AGT formation, thus suggesting a counter‐regulatory role of this receptor in AngII‐induced hypertension." (PMID 34427402, 2021). "Rat models of CKD demonstrated decreased cholinergic responses in the presence of hypertension and elevated renin–angiotensinogen." (PMID 33234591, 2021). "In another renal programming model induced by placental insufficiency in the Sprague Dawley rat, adult offspring developed hypertension in conjunction with increased renin and AGT mRNA, as well as increased ACE activity at 16 weeks of age." (PMID 33669059, 2021). "Ang II, as a key mediator in hypertension, is mainly produced from angiotensinogen (ATG) via angiotensin-converting enzyme (ACE)." (PMID 34413926, 2021). "This study aimed to identify the association between AGT M235T and LVM in Vietnamese patients diagnosed with essential hypertension." (PMID 33681303, 2021). "Materials and Methods:AGT M235T genotyping and 2D echocardiography were performed on 187 Vietnamese subjects with essential hypertension." (PMID 33681303, 2021). "Essential hypertension, for example, is related to some genetic mutations in RAS components, such as the AT1R gene, and to angiotensinogen (AGT) M235T and ACE I/D polymorphisms." (PMID 34834033, 2021). "Our previous study showed that VPA prevented HFD-induced hypertension by downregulating angiotensinogen and its receptor in the kidney." (PMID 31655853, 2020). "Experimentally, a mouse model with transgenic overexpression of angiotensinogen in adipose tissue showed visceral obesity and hypertension." (PMID 32257423, 2020). "Mating of female transgenic mice expressing angiotensinogen with males expressing renin leads to a preeclampsia-like phenotype with hypertension, proteinuria and kidney injury." (PMID 33067549, 2020). "Our findings are coincident to one intervention study promoting the Dietary Approaches to Stop Hypertension (DASH) diet, where AA carriers of the Angiotensinogen genotype (G-6A ANG polymorphism) showed the greatest reduction in DBP." (PMID 33339255, 2020). "Our previous study reported that pan-HDAC inhibitor valproic acid (VPA) has a protective effect in the HFD-induced hypertension through inhibition of angiotensinogen expression in the kidney." (PMID 31655853, 2020). "AGT derived from liver is not only a target for hypertension, but also for many other cardiovascular diseases." (PMID 30530571, 2019). "When comparing test parameters of oxidative stress, the most significant increase in oxidative stress parameters was found in COPD+hypertension patients with the M/M genotype of the AGT gene (compared with controls)." (PMID 32025262, 2019). "In this study, VDD+AmB/LE rats developed hypertension, accompanied by a notable increase in renal protein expression of AGT and ACE, and higher levels of plasma aldosterone." (PMID 31295336, 2019). "Blood pressure reductions produced by i.c.v. injection of AGT ASO was also supported by studies in male Sprague–Dawley rats in which hypertension was induced by either chronic exposure to a cold (5°C) environment or a 2-kidney, 1-clip surgical procedure." (PMID 30530571, 2019). "Mice over expressing 11βHSD1 have severe hypertension due to increased angiotensinogen generation by the liver." (PMID 30678666, 2019).
Hypertension (continued). "In male mice, overexpression of angiotensinogen in adipose tissue results in hypertension, increased adiposity, insulin resistance, glucose intolerance, and reduced insulin-stimulated skeletal muscle glucose uptake." (PMID 31262355, 2019). "The scope of the research findings not only opens doors for potentially new therapeutics of hypertension and many other diseases, but also provides insights into understanding critical physiological and pathophysiological roles mediated by AGT." (PMID 30530571, 2019). "Renin is related to vasoconstriction because of angiotensin, which is converted from angiotensinogen by renin, so the regulation of renin activity is important to hypertension patients." (PMID 31480566, 2019). "These overall findings suggest adipose-derived angiotensinogen contributes to hypertension and metabolic derangements and provide evidence for sex differences in the role of this RAS precursor in systemic glucose homeostasis." (PMID 31262355, 2019). "Comparative analysis of changes in oxidative stress parameters in groups of COPD-only patients and patients with combined COPD and hypertension within one genotype of the AGT gene." (PMID 32025262, 2019). "For instance, it has been demonstrated that in diabetes mellitus and hypertension, the two major risk factors of CKD, the urinary AGT and the intrarenal AngII, are induced." (PMID 31803050, 2019). "The role of ACE and AGT gene polymorphisms in the pathogenesis of comorbid COPD and hypertension is the focus of the research community’s attention." (PMID 32025262, 2019). "AGT can be detected in urine samples of hypertensive humans and in animal models of hypertension and renal disease." (PMID 31680980, 2019). "In the analysis of the odds ratio, we have found a trend suggesting a protective role of the M allele of the AGT gene against COPD, hypertension, and the combination of the two." (PMID 32025262, 2019). "In agreement, previous findings from our laboratory demonstrated that adipocyte expression of angiotensinogen, the precursor to AngII, influences systemic concentrations of AngII and the development of obesity-hypertension in male mice." (PMID 31484552, 2019). "The first study evaluating an AGT ASO for hypertension was reported by Gyurko and colleagues using a well-established spontaneously hypertensive rat (SHR) model." (PMID 30530571, 2019). "Analysis of the available literature suggests the absence of studies on interrelationships between polymorphisms in the ACE and AGT genes and oxidative stress parameters in patients with comorbid COPD and hypertension." (PMID 32025262, 2019). "This study aimed to investigate the association between 4 polymorphisms in RAAS genes (i.e., rs1799752 (ACE), rs699 (AGT), rs5186 (AGTR1), and rs1799998 (CYP11B2)) and hypertension in a Thai population." (PMID 31511791, 2019). "Further analysis through the OMIM database revealed that miR-1182 was annotated with angiotensinogen, a protein related to essential hypertension." (PMID 30975221, 2019). "Overexpression of adipose AGT in mice has been reported to induce hypertension and increase body fat and plasma AGT levels." (PMID 29540174, 2018). "An earlier study showed that in subjects with obesity related hypertension, AGT gene expression in adipose tissue was increased and plasma AGT levels were elevated." (PMID 29540174, 2018). "Further studies have shown that an increase in urinary angiotensinogen is significantly correlated with urinary sodium and precedes hypertension in normo-albuminuric children with type 1 diabetes." (PMID 29600408, 2018). "The involvement of RAAS in cold-induced hypertension is in agreement with previous reports; for example, knockdown or knockout RAAS components angiotensinogen and angiotensin II receptors AT1a ameliorated cold-induced hypertension." (PMID 29560109, 2018). "Another metabolic disorder is hypertension, which occurs when renin produces angiotensin I from angiotensinogen." (PMID 29643982, 2018).
Hypertension (continued). "The role of AGT gene in hypertension is also suggested by studies that showed elevated plasma AGT level by increasing AGT gene-copy number and an increase in blood pressure in TG mice." (PMID 28467442, 2017). "In the present study, we wish to provide further resolution of the contribution of AGT genetic variation (both SNPs and haplotype) to hypertension in the context of Indian population." (PMID 28361007, 2017). "Augmentation of renal proximal tubular angiotensinogen (AGT) expression can promote intrarenal angiotensin formation and the development of associated hypertension and kidney injury." (PMID 28572913, 2017). "Both the SNPs are situated at the core promoter region of the AGT gene and therefore pointing the role of these loci as a central component linking AGT with Hypertension." (PMID 28361007, 2017). "Recently, a new receptor was discovered, able to bind renin and prorenin and increase the conversion of angiotensinogen to Ang I, but its role in hypertension and pharmacological renin inhibition remains to be clarified." (PMID 28598381, 2017). "Renal proximal tubule-specific overexpression of AGT amplifies intrarenal Ang II levels and promotes the development of hypertension and kidney injury in male mice." (PMID 28572913, 2017). "Its effect on hypertension is likely through the renin-angiotensinogen level, sympathetic nerve activity, endothelial function, hypertriglyceridemia, and glucose intolerance." (PMID 29367559, 2016). "AGT M268T with hypertension was established in Caucasian hypertensive sibling pairs, where TT genotype conferred 31% higher risk compared with MM genotype." (PMID 27584680, 2016). "Both 7-locus and 8-locus models suggest that the listed SNPs in AGT, ACE, and AT1R genes were important in association with hypertension." (PMID 25961019, 2015). "The unbalanced function based MDR model can explore the epistasis network of SNPs AGT, ACE, and AT1R of RAS genes and identify strongly significant hypertension association." (PMID 25961019, 2015). "In 2- to 6-locus models of the SNP-SNP interaction, the SNPs of AGT and ACE genes were associated with hypertension (bootstrapping odds ratio [Boot-OR] = 1.972~3.785; 95%, confidence interval (CI) 1.26~6.21; P < 0.005)." (PMID 25961019, 2015). "The 2- to 6-locus models suggest that those SNPs of the AGT and ACE genes were associated with hypertension." (PMID 25961019, 2015). "Our results suggest that AGT, ACE, and AT1R genes have an overall hypertension susceptibility effect." (PMID 25961019, 2015). "Age, hypertension, initial eGFR, plasma hemoglobin, serum uric acid, htTKV, random urine albumin to Cr ratio, urinary AGT/Cr were included in the final model." (PMID 26092580, 2015). "Rat AGT overexpression in RPTCs leads to hypertension, albuminuria and RPTC hypertrophy, and enhances TGF-β1 expression in diabetic AGT-transgenic (Tg) mice." (PMID 26232095, 2015). "Since RAS activation is a major cause of hypertension in ADPKD patients, urinary AGT/Cr and PRA levels were compared among normotensive and hypertensive groups." (PMID 26092580, 2015). "This suggests that the combination of hypertension and a high salt intake is required to enhance the myocardial expression of angiotensinogen and angiotensin II AT1 receptor, and thus, substantial the activation of p38MAPK and TGF-β1." (PMID 25799069, 2015). "We used double transgenic rats harboring both human renin and angiotensinogen genes (dTGR) that develop severe hypertension, target-organ damage, and die untreated within 7–8 weeks." (PMID 24710077, 2014). "Because visceral fat produces angiotensinogen and increases sympathetic nervous activity, MS and T2DM are often associated with hypertension." (PMID 26137510, 2014). "This cascade of events is finally a potent stimulus for angiotensinogen expression and thereby contributes to increase the local synthesis of Ang II and the progression of hypertension and the establishment of renal injury." (PMID 25436148, 2014).
Hypertension (continued). "In this case-control study, we examined possible associations between polymorphisms of the AGT, ACE, and AGTR1 genes and hypertension in the south Indian population age between 30 and 70 years." (PMID 24860821, 2014). "Polymorphism in RAAS gene such as AT1R A1166C (SNP ID: rs5186) angiotensinogen (AGT) M235T and angiotensin converting enzyme insertion/deletion (ACE I/D) has been widely studied and found to be associated with essential hypertension." (PMID 24992666, 2014). "A case-control association study was conducted to investigate a possible involvement of polymorphisms of three RAS genes: AGT M235T (rs699), ACE I/D (rs4340) and G2350A (rs4343), and AGTR1 A1166C (rs5186) in essential hypertensive patients." (PMID 24860821, 2014). "Of 41 SNPs genotyped, rs3789678 and rs2493132 within AGT, rs4305 within ACE, rs275645 within AGTR1, rs3802230 and rs10086846 within CYP11B2 were shown to associate with hypertension." (PMID 24015270, 2013). "According to Chi-square test and logistic regression analysis, rs3789678 within AGT, rs4305 within ACE, rs275645 within AGTR1, rs3802230 within CYP11B2 were shown to associate with hypertension." (PMID 24015270, 2013). "Recently, the E-boxes in the promoter regions of renin and angiotensinogen were shown to be direct targets of Usf1 and Usf2 and suggested to be involved in the pathogenesis of both hypertension and renal injury." (PMID 23653383, 2013). "In agreement, former studies showed that omega-3 PUFAs significantly decreased systemic arterial blood pressure in hypertension models of transgenic rats expressing the human renin and angiotensinogen genes and diabetic spontaneously hypertensive rats." (PMID 24303178, 2013). "The objective of the present study was to systemically examine the association between polymorphisms in the RAAS candidate genes (REN, AGT, ACE, AGTR, and CYP11B2) and hypertension." (PMID 24015270, 2013). "According to the chi-square test P values (P<0.05) and odds ratios, rs3789678 and rs2493132 within AGT, rs4305 within ACE, rs275645 within AGTR1, rs3802230 and rs10086846 within CYP11B2 were shown to associate with hypertension." (PMID 24015270, 2013). "Specifically, rats transgenic for human renin and angiotensinogen develop early hypertension, cardiac hypertrophy, and renal damage, with marked albuminuria and focal cortical necrosis." (PMID 23902712, 2013). "We recently reported that PRR knockdown in the brain attenuated Ang II-dependent hypertension in human renin and AGT double transgenic mice." (PMID 23316344, 2012). "Human renin and AGT double transgenic mice exhibit Ang II-dependent hypertension, which can be attenuated by AVP antagonist suggesting an interaction between the brain RAS and AVP in hypertension." (PMID 23316344, 2012). "In rats, transgenic for both the human renin and angiotensinogen genes, hypertension and kidney damage developed which was largely independent of BP elevation but was dependent on an androgen component." (PMID 21603136, 2011). "Renin has become an attractive target in controlling hypertension because of the high specificity towards its only substrate, angiotensinogen." (PMID 22372967, 2011). "Hypothetically, if a loss-of-function miRSNP occurred in the AGTR1, ACE, AGT, REN, or ATP6AP2 gene, an increased incidence of hypertension, cardiac/vascular remodeling, and atherosclerosis would be observed." (PMID 20948563, 2010). "Elevated serum levels of AGT are often recognized as the cause of hypertension, because higher AGT concentrations lead to supernormal Ang II production." (PMID 20613959, 2010). "In severe obesity, adipose tissue can be an important source of AGT, potentially contributing to the development of hypertension and the vascular complications of metabolic syndrome." (PMID 20613959, 2010).
Hypertension (continued). "Among the many known adipocytokines, angiotensinogen has been found to be produced by adipocytes, and angiotensinogen can promote the development of hypertension by stimulating the production of angiotensin II." (PMID 19754934, 2009). "Further, IL-6 induces an increase in plasma angiotensinogen and angiotensin II, leading to development of hypertension." (PMID 18416854, 2008). "The Tsukuba hypertensive mice (THM), which express the human REN and angiotensinogen genes, have been provento develop hypertension." (PMID 17641732, 2007). "Recently, transgenic rodent models have been developed that over express both human REN and angiotensinogen, which leads to hypertension via chronic overproduction of Ang II." (PMID 17641732, 2007). "Hypertensive mice that express the human renin and angiotensinogen genes are used as a model for human hypertension because they develop hypertension secondary to increased renin-angiotensin system activity." (PMID 17641732, 2007). "Although in most surveys the prevalence of hypertension appears to be equal in women and men, sex-specific effects of ACE or AGT genes on hypertension have been reported recently." (PMID 15642127, 2005). "Of the 25 studies included in the present meta-analysis, the present study was the only one in which the AGT T235T genotype decreased odds for hypertension." (PMID 15642127, 2005). "A common molecular variant of angiotensinogen (AGT), the precursor of potent vasoactive hormone angiotensin II, has been incriminated as a marker for genetic predisposition to essential hypertension in some ethnics." (PMID 15811183, 2005). "Many recent case-control studies have suggested a significant relationship between M235T (the substitution of threonine for methionine at position 235 codon) polymorphism of the angiotensinogen (AGT) gene and hypertension." (PMID 11434422, 2001). "Conversely, ischemic stroke exacerbates hypertension through neurohumoral mechanisms: damaged brain tissue releases angiotensinogen, which is converted to angiotensin II in circumventricular organs, leading to sympathetic overactivation and neurogenic hypertension." (PMID 40723792, 2025). "An innovative and promising therapeutic strategy for the control of hypertension involves the inhibition of hepatic angiotensinogen (AGT) synthesis, thereby reducing the formation of angiotensin I and II and consequently attenuating the activation of angiotensin II type 1 and type 2 receptors." (PMID 41226756, 2025). "Zilebesiran is an siRNA targeting hepatic angiotensinogen, meant for the treatment of hypertension." (PMID 39808369, 2025). "Finally, studies in animal models of hypertension have shown that targeting angiotensinogen by CRISPR-Cas9 gene editing results in a sustained BP reduction." (PMID 40299361, 2025). "EIF2AK2 encodes the protein kinase R (PKR) on chromosome 2, which animal studies have shown may affect hypertension through modulation of angiotensinogen and TGF-β, reducing fibrosis and apoptosis." (PMID 39538414, 2025). "Genetic variations in AGT lead to alterations in plasma AGT concentrations, which may contribute to the development of hypertension, CAD, and myocardial infarction." (PMID 40640196, 2025). "In young male and aging female offspring programmed for hypertension by placental insufficiency, the enhanced responsiveness to acute ANG II is testosterone-dependent, and testosterone plays an important role in maintaining the hypertension through enhancement of intrarenal angiotensinogen." (PMID 40356772, 2025). "Increased AGT expression from visceral adipose tissue may contribute, in part, to the development of hypertension and metabolic abnormalities in PA." (PMID 39125667, 2024). "Preclinical and clinical evidence has recently suggested that antihypertensive drugs based on silencing hepatic AGT production through RNA interference (RNAi) could improve adherence to hypertension treatment." (PMID 39852196, 2024).